ATP5PO (ATP synthase peripheral stalk subunit OSCP)
Description:
Subunit OSCP, of the mitochondrial membrane ATP synthase complex (F(1)F(0) ATP synthase or Complex V) that produces ATP from ADP in the presence of a proton gradient across the membrane which is generated by electron transport complexes of the respiratory chain. ATP synthase complex consist of a soluble F(1) head domain - the catalytic core - and a membrane F(1) domain - the membrane proton channel. These two domains are linked by a central stalk rotating inside the F(1) region and a stationary peripheral stalk. During catalysis, ATP synthesis in the catalytic domain of F(1) is coupled via a rotary mechanism of the central stalk subunits to proton translocation (Probable). In vivo, can only synthesize ATP although its ATP hydrolase activity can be activated artificially in vitro (By similarity). Part of the complex F(0) domain. Part of the complex F(0) domain and the peripheric stalk, which acts as a stator to hold the catalytic alpha(3)beta(3) subcomplex and subunit a/ATP6 static relative to the rotary elements (By similarity).
Synonyms: OSCP; ATP5O; ATPO; HMC08D05; MC5DN7
Tractability: Small molecule: a structure with a bound ligand is known. Antibody: its Gene Ontology location is reachable by antibodies, with high confidence. PROTAC: UniProt records ubiquitination sites on it; ubiquitination databases record sites on it.
Gene: Protein-coding gene on chromosome 21 (33,901,028 to 33,915,853, reverse strand). Ensembl gene ENSG00000241837.
Subcellular location: Mitochondrion; Mitochondrion inner membrane
Subcellular location (Human Protein Atlas): Mitochondria
Pathways (Reactome):
Metabolism: Formation of ATP by chemiosmotic coupling
Metabolism of proteins: Mitochondrial protein degradation
Organelle biogenesis and maintenance: Cristae formation
Gene Ontology:
Molecular function: protein binding; proton-transporting ATP synthase activity, rotational mechanism; ATP hydrolysis activity; estradiol binding; protein-containing complex binding
Biological process: proton motive force-driven mitochondrial ATP synthesis; ATP biosynthetic process; proton motive force-driven ATP synthesis; proton transmembrane transport; cellular response to cAMP; cellular response to cytokine stimulus
Cellular component: mitochondrion; nucleus; plasma membrane; proton-transporting ATP synthase complex; mitochondrial inner membrane; cell surface; membrane
Genetic constraint (gnomAD): Loss-of-function variants: 13 observed, 23.75 expected, observed/expected ratio (o/e) 0.55, 90% interval 0.35 to 0.87. The upper end of that interval is the gene's LOEUF score, 0.87, which puts it in group 3 of 6, group 1 being the genes least tolerant of losing a copy. Missense variants: 239 observed, 261.91 expected, observed/expected ratio (o/e) 0.91, 90% interval 0.82 to 1.02. Synonymous variants: 104 observed, 97.36 expected, observed/expected ratio (o/e) 1.07, 90% interval 0.91 to 1.26.
Gene-disease validity (ClinGen):
ClinGen rates the evidence that ATP5PO causes each of these diseases.
mitochondrial disease (autosomal recessive): Strong.
Homologues: Orthologues: chimpanzee ATP5PO (93% identical), rabbit ATP5PO (90% identical), pig ATP5PO (89% identical), guinea pig ATP5PO (85% identical), mouse Atp5po (82% identical), rat Atp5po (82% identical), dog ATP5PO (77% identical), tropical clawed frog atp5po (62% identical), zebrafish atp5po (60% identical), Drosophila melanogaster ATPsynO (42% identical), Caenorhabditis elegans atp-3 (41% identical).
Diseases named in the same sentence as ATP5PO in open-access papers:
ATP5PO is named in the same sentence as 36 diseases in open-access papers, as found by Europe PMC text mining. Sharing a sentence is not in itself a finding about the gene and the disease. The quoted sentences say what the papers report.
COVID-19 (5 papers, 2023 to 2025). A disease caused by infection with severe acute respiratory syndrome coronavirus 2. "This study demonstrates that there is a persistent increased activation of nuclear-encoded OXPHOS genes namelyCOX7C, COX7A2, ATP5PO, ATP5F1C and NDUFB8 in blood tissue immediately following COVID-19 recovery, and then a time-dependent tapering off of these genes." (PMID 41141600, 2025).
lung carcinoma (2 papers, 2021 to 2024). "Among them, a number of proteins related to mitochondrial biogenesis were upregulated in BrM lesions as compared to paired primary lung cancers, including NDUFAF2, SDHB, COX5A, and ATP5PO." (PMID 39593114, 2024).
Menière's disease (1 paper, 2021). "From our identified miRNAs, miRNA-1299 was identified as the most promising biomarker for Menière's disease since it is differentially regulated in both perilymph and serum of Menière's patients, and is predicted to target R3HDM2, SCP2, and ATP5PO mRNA." (PMID 34220670, 2021).
degenerative diseases (2 papers, 2019 to 2025). "IF regulates lipid metabolism primarily via genes including FABP4, WNT10B, PCK1, PLIN1, LEPR, and ADIPOQ, providing energy for cold adaptation, whereas PF positively influences in vivo degenerative diseases mainly through genes such as ATP5F1A, ATP5PO, SDHB, NDUFS8, SDHA, and COX5A." (PMID 40136641, 2025). "In contrast, in PF tissue, genes like ATP5F1A, ATP5PO, SDHB, NDUFS8, SDHA, and COX5A play roles within the neurodegenerative disease pathway, and PF tissue has a positive impact on the process related to degenerative diseases." (PMID 40136641, 2025).
ATP5PO also shares sentences with these, for which no sentence is quoted: tumor (10 papers); cancer (5); clear cell renal cell carcinoma (3); gastric cancer (3); thyroid autoimmunity (3); infection (2); Parkinson disease (2); thyroid (2); Autoimmunity (1); breast carcinoma (1); celiac disease (1); copy number variation (1); diabetes (1); diabetic cardiomyopathy (1); Down syndrome (1); gestational diabetes mellitus (1); hyperprolactinemia (1); Infertility (1); Insulin resistance (1); intraepithelial neoplasia (1); leukemia (1); mesothelioma (1); multiple sclerosis (1); papillary thyroid carcinoma (1); preeclampsia (1); prostate carcinoma (1); thyrotoxicosis (1); trisomy 21 (1); type-2 diabetes (1); virus infection (1).
A further 2 diseases each share a sentence with ATP5PO in 1 paper.